MAF1 (MAF1 negative regulator of RNA polymerase III)
Diseases named in the same sentence as MAF1 in open-access papers (continued):
Sharing a sentence is not in itself a finding about the gene and the disease.
Stroke (3 papers, 2023 to 2025). Sudden impairment of blood flow to a part of the brain due to occlusion or rupture of an artery to the brain. "MAF1 protein expression was notably increased, primarily in the dephosphorylated/active form during the first two weeks after stroke in the peri-infarct cortex compared to the sham control." (PMID 39363536, 2024). "In an in vivo permanent stroke model, MAF1 is notably upregulated in the peri-infarct tissue of the cerebral cortex during the critical repair period of 7 to 14 days after stroke onset, gradually returning to background levels at 2 months." (PMID 39363536, 2024). "Similarly, Maf1 is a transcriptional regulator that suppresses spontaneous neural repair, where knocking down Maf1 using AAV‐mediated delivery in a mouse PT stroke model enhanced neural plasticity and functional recovery." (PMID 37551863, 2023). "MAF1’s role in repressing energy-consuming Pol III-dependent transcription suggests that it is pro-survival during stress conditions, such as the acute phase of stroke." (PMID 39363536, 2024). "Targeting MAF1 through small molecule inhibitors, AAV-mediated knockdown, or RNA-based nanoparticle delivery could be a useful approach for stroke management during the recovery phase." (PMID 39363536, 2024). "In addition, the complex dynamic nature of post-stroke immune responses could influence the outcome resulted from MAF1 knockdown, and therefore energy conservation may not be the only key factor for the determination of cell survival." (PMID 39363536, 2024).
cardiac hypertrophy (2 papers, 2019 to 2020). "To further clarify the relationship between Maf1 and cardiac hypertrophy, we first conducted gain- and loss-of-function studies with Maf1 knockout mice and by adenoviral overexpression of Maf1 in WT mice." (PMID 31695767, 2019). "Therefore, to explore the effect of Maf1 on cardiac hypertrophy and the underlying mechanism, we studied the role of Maf1 in the process of cardiac hypertrophy both in vivo and in vitro." (PMID 31695767, 2019). "Thus, both the in vivo and in vitro gain- and loss-of-function experiments verified that Maf1 could ameliorate cardiac hypertrophy and cardiac dysfunction." (PMID 31695767, 2019). "We found that both RNA pol III inhibitor and U0126 inhibited the expression of 5SrRNA, tRNALeu and Brf1 and improved Maf1 knockdown-promoted cardiac hypertrophy." (PMID 31695767, 2019). "To further clarify the effect of Maf1 on cardiac hypertrophy, we examined the effect of Maf1 on PE-induced cardiomyocyte hypertrophy." (PMID 31695767, 2019). "Taken together, we discovered for the first time that Maf1 has an inhibitory effect on the development of cardiac hypertrophy." (PMID 31695767, 2019). "Accordingly, these results suggest that upregulation of Maf1 significantly ameliorates AB-induced cardiac hypertrophy and heart failure in vivo." (PMID 31695767, 2019). "The results imply that the ERK1/2 signaling pathway plays a pivotal role in mediating the inhibitory effect of Maf1 on cardiac hypertrophy." (PMID 31695767, 2019). "After confirming the successful knockout of Maf1, AB surgery was performed to induce cardiac hypertrophy by pressure overload." (PMID 31695767, 2019). "Both the in vivo and in vitro gain- and loss-of-function experiments by Maf1 knockout (KO) mice and adenoviral transfection were used to verify the role of Maf1 in cardiac hypertrophy." (PMID 31695767, 2019). "In contrast, compared with adenoviral-GFP injected mice, mice injected with adenoviral-Maf1 showed significantly ameliorated AB-induced cardiac hypertrophy." (PMID 31695767, 2019). "In the present study, we found that total and nuclear expression of Maf1 was significantly upregulated in AB-induced cardiac hypertrophy, suggesting that changes in Maf1 might play a role in the development of hypertrophy." (PMID 31695767, 2019). "The interaction between Maf1 and ERK1/2 implies that Maf1 might regulate cardiac hypertrophy through RNA pol III inhibition by directly binding ERK1/2." (PMID 31695767, 2019). "However, application of an RNA pol III inhibitor markedly improved Maf1 knockdown-promoted cardiac hypertrophy." (PMID 31695767, 2019). "Taken together, these results indicate that Maf1 might inhibit cardiac hypertrophy through negative regulation of RNA pol III, which eventually leads to reduced protein synthesis." (PMID 31695767, 2019). "Moreover, ERK1/2 was identified as a regulator of RNA pol III, and ERK1/2 inhibition by U0126 significantly repressed Maf1 knockdown-promoted cardiac hypertrophy accompanied by suppressed RNA pol III transcription." (PMID 31695767, 2019). "Meanwhile, adenoviral overexpression of Maf1 could ameliorate cardiac hypertrophy and heart failure." (PMID 31695767, 2019). "To determine whether Maf1 participates in the cardiac hypertrophy process, we examined the changes in total and nuclear Maf1 expression in pressure overload-induced cardiac hypertrophy." (PMID 31695767, 2019). "Although Maf1 is a key negative regulatory molecule of RNA pol III, whether Maf1 regulates cardiac hypertrophy through pol III remains unknown." (PMID 31695767, 2019). "Therefore, to further explore whether the ERK1/2 signaling pathway plays a critical role in Maf1-regulated cardiac hypertrophy, we detected the changes in the ERK1/2 signaling pathway in AB or PE-induced cardiac hypertrophy." (PMID 31695767, 2019). "Thus, according to our findings, we speculated that Maf1 might regulate cardiac hypertrophy by modulating RNA pol III activity via the ERK1/2 signaling pathway." (PMID 31695767, 2019).
cardiac hypertrophy (continued). "However, whether Maf1 inhibits cardiac hypertrophy by repressing pol III transcription is still unclear." (PMID 31695767, 2019). "Thus, we speculated that Maf1 overexpression negatively regulated cardiac hypertrophy mainly by blocking ERK1/2 signaling." (PMID 31695767, 2019). "However, whether Maf1 participates in cardiac hypertrophy process remains unclear." (PMID 31695767, 2019). "However, whether Maf1 regulates of cardiac hypertrophy remains unclear." (PMID 31695767, 2019). "Although Maf1 is a key regulatory factor of RNA pol III and might affect protein synthesis, whether Maf1 can regulate cardiac hypertrophy remains poorly understood." (PMID 31695767, 2019). "Coimmunoprecipitation demonstrated that Maf1 could directly bind ERK1/2, suggesting that ERK1/2 might be a core target in the Maf1-mediated inhibitory effects on RNA pol III and cardiac hypertrophy." (PMID 31695767, 2019). "This phenotype indicated that knocking out of Maf1 does not affect cardiac hypertrophy in nonstress conditions." (PMID 31695767, 2019). "In conclusion, our in vivo and in vitro studies reveal that Maf1 can directly bind ERK1/2 and ameliorate cardiac hypertrophy via negative regulation of RNA pol III transcription, thus providing a new potential clinical treatment target for cardiac hypertrophy." (PMID 31695767, 2019). "Additionally, IP analysis demonstrated that Maf1 could directly bind ERK1/2, suggesting Maf1 could interact with ERK1/2 and then inhibit RNA pol III transcription so as to attenuate the development of cardiac hypertrophy." (PMID 31695767, 2019). "It suggests that Maf1/ERK/pol III axis may be an important mechanism for Maf1 in regulating pol III and is an important supplement to the mechanism of inhibiting pol III transcription by direct interaction between Maf1 and pol III in the context of cardiac hypertrophy." (PMID 31695767, 2019). "In addition, the gain-of-function experiments using recombinant adenoviruses confirmed the negative effect of Maf1 on pol III transcription in the process of cardiac hypertrophy." (PMID 31695767, 2019).
liver cancer (2 papers, 2024 to 2025). An epithelial or non-epithelial malignant neoplasm that arises from the liver. "In a liver cancer study, MAF1 was reported to suppress AKT/mTOR signaling by activating PTEN transcription and inhibiting cell cycle progression." (PMID 39833662, 2025). "Our recent studies in liver cancer models in vitro and in vivo further revealed that overexpression of MAF1 inhibits tumour cell growth through direct binding to the promoter of PTEN." (PMID 39363536, 2024). "MAF1 has been shown to bind to the PTEN promoter and activate PTEN transcription, suppressing mTORC1 signalling activity as a feed-forward mechanism in liver cancer cells." (PMID 39363536, 2024).
Alzheimer disease (1 paper, 2024). A progressive, neurodegenerative disease characterized by loss of function and death of nerve cells in several areas of the brain leading to loss of cognitive function such as memory and language. "Our results clarify the important role and mechanism of the Maf1-NMDAR1 signalling pathway in stabilizing synaptic structure, neuronal function and behaviour during Alzheimer’s disease pathogenesis." (PMID 38226680, 2024). "Maf1 regulates the expression of NMDAR1 by binding to the promoter of the Grin1 gene and could represent a potential therapeutic target for Alzheimer’s disease." (PMID 38226680, 2024).
Co-infection (1 paper, 2014). "Co-infection experiments using type I and type I:Δmaf1 parasites showed the predicted HMA dependency on MAF1; type I parasites exhibit HMA in contrast to the clear loss of HMA in type I:Δmaf1 parasites." (PMID 24781109, 2014).
cyst (1 paper, 2018). A sac-like closed membranous structure that may be empty or contain fluid or amorphous material. "Inducible deletion (via inducible cre-mediated recombination systems, for example) of the entire MAF1 locus in mice would also help to determine how MAF1b expression mediates changes in cyst size and/or bradyzoite replication." (PMID 30333181, 2018).
invasive breast carcinoma (1 paper, 2023). A carcinoma that infiltrates the breast parenchyma. "MAF1 amplification is frequent in invasive breast cancer and co-occurs with MYC." (PMID 37801436, 2023).
lung carcinoma (1 paper, 2021). "Together, our study reveals a novel role of Maf1-UPRmt axis in mediating rapamycin’s enhancing effect on IR sensitivity in A549 lung cancer cells." (PMID 33640883, 2021). "Our study implicates Maf1 regulation of UPRmt as a novel mechanism mediating rapamycin’s enhancing effect on radiosensitivity of lung cancer cells." (PMID 33640883, 2021). "Here we show that Maf1 is required for rapamycin to increase radio-sensitivity in A549 lung cancer cells." (PMID 33640883, 2021). "The results suggest that genetically or pharmacologically activating Maf1 could improve radiotherapy for lung cancers or even other cancers, especially those that are resistant to rapamycin or deregulated in mTOR activity." (PMID 33640883, 2021).
myeloma (1 paper, 2020). "Collectively, the generated protein–protein interaction analysis indicated a significant correlation between the driver oncogenomic mutation KRAS and MAF1 and abnormal basal autophagy in myeloma PCs." (PMID 32085480, 2020).
parasite infection (1 paper, 2014). "MAF1 also altered host cells' response to parasite infection; murine monocytes growing in cell culture secreted a different constellation of immunomodulatory proteins when infected with MAF1-expressing type II versus wild-type type II parasites." (PMID 24781144, 2014).
prostate carcinoma (1 paper, 2014). A carcinoma that arises from epithelial cells of the prostate gland. "We further examined whether Maf1 expression might be deregulated in human prostate cancer where PTEN is frequently lost." (PMID 25502566, 2014).
tumor (12 papers, 2006 to 2025). "Phosphatase and tensin homolog (PTEN) is a major tumor suppressor and inhibitor of mTOR signaling that is activated by MAF1." (PMID 39833662, 2025). "The nuclear localization of Maf1 exerts its tumor-suppressive function through various regulatory mechanisms, including the inhibition of tRNA biosynthesis, modulation of lipid metabolism, and promotion of PTEN expression." (PMID 41339318, 2025). "Previous reports indicated the multifaceted role of Maf1 in tumorigenesis, suggesting its complex involvement in tumor development." (PMID 41339318, 2025). "Due to its ability to suppress RNA Pol III activity, Maf1 has been proposed as a potential tumor suppressor." (PMID 41339318, 2025). "Mice were randomly divided into 3 treatment groups: Mock + sh-NC, hrCHI3L1 + sh-NC and hrCHI3L1 + sh-MAF-1, and tumor growth was monitored using small animal live imaging." (PMID 37838657, 2023). "In comparison, the tumor growth rate and size in the hrCHI3L1 + sh-MAF-1 group were significantly lower than those in the hrCHI3L1 + sh-NC group." (PMID 37838657, 2023). "Inhibiting Maf1 expression can induce cancerous transformation in hepatocellular cells and Maf1 overexpression can suppress tumor growth in vivo." (PMID 33640883, 2021). "Collectively, these results support the idea that Maf1 is a key downstream target of PTEN that contributes to the ability of PTEN to function as a tumor suppressor." (PMID 25502566, 2014). "Tumorigenecity assays revealed that while all mice formed tumors, the onset of visible tumors as well as tumor growth was significantly delayed with increased Maf1 expression." (PMID 25502566, 2014). "Here, we show that Maf1 is a key downstream target of PTEN that drives both its tumor suppressor and metabolic functions." (PMID 25502566, 2014). "Consistent with its role as a tumor suppressor, Maf1 reduces anchorage-independent growth and tumor formation in mice." (PMID 25502566, 2014). "Our studies identify Maf1 as a novel PTEN target and provide the first evidence that Maf1 functions as a tumor suppressor." (PMID 25502566, 2014). "Consistent with this idea, enhanced expression of Maf1 significantly represses both anchorage-independent growth and tumor formation in mice." (PMID 25502566, 2014). "Our results have identified a novel role for Maf1 in suppressing both lipid biogenesis and tumor formation." (PMID 25502566, 2014). "Additionally, HCC patients with high Aurora-A expression and elevated Maf1 in tumor tissues were positively correlated with a poor prognosis." (PMID 41339318, 2025). "To explore the biological role of Maf1 and to investigate how it is regulated, we asked whether the tumor suppressor PTEN modulates Maf1 expression." (PMID 25502566, 2014). "In contrast, matched tumor tissue displayed a marked reduction in nuclear Maf1 expression." (PMID 25502566, 2014). "In addition, the T > C variation of rs10877887 may have strong affinity with Myeloid zinc finger 1 (MAF1), a transcription factor which can promote the activity of Axl promoter, resulting in tumor cell migration, invasion and metastasis." (PMID 30619739, 2018). "Maf1 is a well-known RNA polymerase III repressor and functions as a tumor suppressor due to its role in inhibiting tRNA synthesis." (PMID 41339318, 2025). "Within UALCAN, we queried the Clinical Proteomic Tumor Analysis Consortium (CPTAC) and the International Cancer Proteogenome Consortium (ICPC) datasets to analyze MAF1 expression." (PMID 37801436, 2023). "In tumor cells, having more RPC32α-incorporated Pol III isoform will render these isoforms refractory to MAF1-mediated repression, thereby meeting the high demands of RNA Pol III transcription in tumor cells." (PMID 31160378, 2019). "Within the tumour samples, we examined the correlation between SABT1 and the downstream regulated genes: IL-4, IL-13 and MAF-1 using Pearson's correlation coefficient." (PMID 19642980, 2009).
tumor (continued). "Maf1 is recognized as an RNA pol III suppressor and a promising candidate for tumor suppression." (PMID 41339318, 2025). "It will be interesting to determine whether in some other tumor cells, the Maf1 protein itself, rather than signaling to Maf1, is debilitated." (PMID 17205138, 2006).
cancer (11 papers, 2014 to 2025). A tumor composed of atypical neoplastic, often pleomorphic cells that invade other tissues. "Future studies will be directed towards understanding how aberrant expression or function of Maf1 contributes to risk for metabolic diseases and cancer." (PMID 25502566, 2014). "Thus, it is likely that the decrease in Maf1 expression observed in Pten-deficient mouse models and human cancer, and the concordant induction of Maf1 gene targets, contributes to the development or progression of the disease." (PMID 25502566, 2014). "Thus, Maf1 represents a novel link between lipid metabolism and oncogenic transformation providing a new molecular basis for the strong association between obesity and cancer." (PMID 25502566, 2014). "Given the conflicting reports on the dual roles of Maf1 in tumorigenesis, we analyzed the expression of Maf1 mRNA in various cancers using the TCGA datasets." (PMID 41339318, 2025). "Our results support the idea that deregulation of this pathway in cancer cells results in decreases in cellular Maf1, resulting in both abnormal growth and lipid synthesis." (PMID 25502566, 2014). "In contrast, in colorectal cancer (CRC), Maf1 expression is associated with an unfavorable outcome in tumors with microsatellite instability (MSI), highlighting the context-dependent nature of its role in cancer." (PMID 41339318, 2025). "For HCC patients with high expression of both Aurora-A and Maf1, targeting Aurora-A may be a promising strategy in cancer therapy." (PMID 41339318, 2025). "Currently, it is unclear if MAF1 is universally deregulated in human cancers." (PMID 37801436, 2023). "Maf1 is an mTORC1 effector that has significant roles in cancer biology." (PMID 33640883, 2021). "We wondered if Maf1, a poorly studied mTOR effector could also have roles in radio-resistance in cancer cells." (PMID 33640883, 2021). "Maf1 expression is diminished with loss of PTEN in both mouse models and human cancers." (PMID 25502566, 2014). "Given that liver and prostate tissues from Pten conditional mutant mice exhibit reductions in Maf1 expression, we tested whether Maf1 expression might be similarly deregulated in PTEN-deficient human cancers." (PMID 25502566, 2014). "Together, these results are the first to suggest the idea that Maf1 expression may be deregulated in human cancer." (PMID 25502566, 2014). "In Maf1-overexpressing HCC cells, the treatment of Aurora-A inhibitor MLN8237 showed higher effectiveness in eradicating cancer cells." (PMID 41339318, 2025). "Maf1 amounts are regulated through a critical cellular pathway involving PTEN/PI3K/Akt/FoxO1, which is deregulated in many human cancers." (PMID 25502566, 2014). "Our study demonstrates that Aurora-A is a novel kinase in regulating Maf1 function and targeting Aurora-A may be a promising strategy in cancer therapy, particularly for HCC patients with higher expression levels of Maf1 and Aurora-A." (PMID 41339318, 2025). "To date, the analysis of MAF1 expression in human cancers has been limited and has not been extensively studied." (PMID 37801436, 2023). "MAF1 is a terminal node in the target of rapamycin (TOR) signaling network, which drives cell growth, controls metabolism, and contributes to metabolic disease, cancer, and aging." (PMID 25934505, 2015). "As a well-known mTOR effector, Maf1’s role in cancer radiosensitivity has not been investigated." (PMID 33640883, 2021). "Our study uncovers a non-canonical, oncogenic role of Maf1 in HCC and highlights the Aurora-A-Maf1 axis as a promising target for personalized cancer therapy." (PMID 41339318, 2025).